BRAF (B-Raf proto-oncogene, serine/threonine kinase)
Diseases named in the same sentence as BRAF in open-access papers (continued):
Sharing a sentence is not in itself a finding about the gene and the disease.
tumor (continued). "On the other hand, if a combination would work exclusively synergistic in a specific tumor cell population (e. g., BRAF-mutant cells) and not in other cells (i. e., BRAF-wild type, or non-malignant cells), this would amplify the specific effect of the inhibitors." (PMID 26018524, 2015). "Furthermore, a considerable majority of low-advanced tumours did not allow to demonstrate lower sensitivity to radioiodine therapy in BRAF(+) patients." (PMID 26177218, 2015). "We electroporated these DCs either without RNA (mock) or with a panel of 16 different RNAs encoding tumor antigens, or parts thereof (MelanA, NRAS, BRAF, GNAQ, GNA11, and WT1), either mutated or not, and either linked to the lysosomal targeting signal DC-LAMP or not." (PMID 26824052, 2015). "Notably, the patient's tumor did not harbor any mutations or amplifications in other EGFR signaling members such as EGFR and BRAF." (PMID 24550739, 2014). "Therefore even with highly active drugs such as targeted therapy in the BRAF mutant population or with the new checkpoint inhibitors (CTLA-4 and PD-1/PDL-1 inhibitors) which potentiate the immune response in tumor, relapse at immune privileged sites will continue to be problematic." (PMID 25516805, 2014). "This suggests that non-V600 BRAF mutations may be sufficient to initiate cancer but may require further alterations in the RAS pathway for tumor progression, as non-V600 mutations are not as potent in activating the RAS pathway as V600 mutation in BRAF." (PMID 25415047, 2014). "No single tumor was identified that harbored KRAS and BRAF mutations." (PMID 24765171, 2014). "In the overall analysis, significant associations were found between most anthropometric factors and risk of KRAS-mutated and BRAF wild type tumours, whereas only BMI was associated with KRAS wild type tumours, and none of the anthropometric factors were associated with risk of BRAF-mutated CRC." (PMID 24918610, 2014). "That the influence of PTEN expression on prognosis was more pronounced in tumours without BRAF or NRAS mutations is a new observation, and suggests that PTEN loss may be a key biomarker in BRAF-wildtype tumours." (PMID 24830350, 2014). "It has been reported that BRAF and KRAS mutations do not occur concomitantly within the same tumor, as simultaneous mutation in the same RAS/RAF/MEK/ERK signal pathway are redundant for the tumor cells." (PMID 25013473, 2014). "From a practical perspective, small biopsies may not adequately represent a tumor's full mutational profile, particularly for later arising but prognostically important mutations such as those in the KRAS and BRAF genes." (PMID 24742923, 2014). "Concurrent somatic BRAF and KRAS mutations within the same tumor specimen have not been reported." (PMID 25013473, 2014). "For instance, it has been clarified that ligands of VDAC proteins selectively induce non-apoptotic cell death in tumor cells harbouring mutations in the oncogenes HRAS, KRAS, or BRAF by comparing the binding proteins of erastin A6 and erastin B2, an erastin analogue that lacks its activity." (PMID 23431365, 2013). "As such, the effects of NRAS/BRAF status on survival may reflect an enhanced effect of treatment or, alternatively, tumor biology independent of drug therapy." (PMID 23673558, 2013). "In fact, it has recently been reported that administration of the mutant BRAF inhibitors alone resulted in the increased infiltration of granzyme positive CD8+ T cells in tumors without inhibiting general immune responses, which was correlated with tumor reduction and necrosis." (PMID 23755373, 2013). "They reflect the macroscopic appearance of human BRAF mutant tumors (flat nonpolypoid neoplasia), their pathomorphologic characteristics (serrated and mucinous appearance), their genetic features (e.g., microsatellite instability), and their response to targeted therapeutics." (PMID 23845441, 2013).
tumor (continued). "The higher prevalence of BRAF-mutated tumours in women, together with the lack of prognostic impact of BRAF mutations in female CRC, indicates the possibility of a link between hormonal factors and BRAF mutation status in CRC." (PMID 24020794, 2013). "While targeted therapy such as BRAF and MEK inhibitors can effect early shrinkage of tumor bulk increasing the resectability of target lesions, the durability of response with this class of treatment has not been uniformly reported and may not have significant impact on overall survival." (PMID 24499550, 2013). "For example, in cell cultures, the V600E mutation increases BRAF activity independent of KRAS and shows lower transforming activity, while inhibition of MEK with small molecules prevents tumor growth in BRAF-mutant tumor xenografts but not in KRAS-mutant counterparts." (PMID 24367680, 2013). "Notably, BRAF and NRAS mutations were found to be mutually exclusive (p < 0.001), with no tumor harboring mutations in both genes." (PMID 23673558, 2013). "In addressing this issue, we showed that concomitant administration of BRAF and MEK inhibitors abrogated paradoxical BRAF inhibitor-induced MAPK signalling in cells, reduced the occurrence of skin lesions in rats, and enhanced the inhibition of human tumor xenograft growth in mouse models." (PMID 23844038, 2013). "In addition to a reduced potential for BRAF inhibitor-activated growth of wild-type RAF cells, the combination of dabrafenib with a MEK inhibitor (trametinib) showed enhanced efficacy in a BRAFV600E tumor xenograft model." (PMID 23844038, 2013). "This is a retrospective study, and alterations in other kinases such as KRAS, BRAF, and cMET that drive tumor growth were not investigated in this study; thus it is possible that the survival and response were affected, at least in part, by those underlying biomarkers." (PMID 23557218, 2013). "Finally, we investigated whether BRAF and MEK inhibitor co-administration would also be advantageous in reducing BRAFV600E tumor growth." (PMID 23844038, 2013). "Thus, in patients with previously tested BRAF status of the primary tumor or extracranial metastases, no additional analysis of the brain metastasis is required." (PMID 22385786, 2012). "CIMP-positive CRCs have been reported to have distinct clinicopathologic profiles compared to their CIMP-low/negative counterparts; older age, female sex, proximal tumor location, poorly differentiated or mucinous histology, and high rates of MSI and BRAF mutation." (PMID 21827707, 2011). "While this might have interesting scientific consequences, the clinical relevance of a tumor containing a small amount of mutant BRAF cells is none, as these patients would not be expected to benefit from BRAF inhibitors." (PMID 22175026, 2011). "Importantly, these responses were not only seen in patients with BRAFV600E but also in BRAFV600K and BRAFV600G mutations, and possibly shows the wider range of activity of selective BRAF inhibitors that are not limited only to BRAFV600E-mutant tumours." (PMID 21139585, 2011). "Thus a tumor with a KRAS mutation generally does not also harbor a BRAF mutation, as KRAS is upstream of BRAF in the same pathway." (PMID 21092299, 2010). "To further exclude the possibility of pathological misclassification of endometrioid, clear cell or LGS tumours in the mutation-negative cases, we also tested for mutations commonly associated with these subtypes in KRAS (exon 2), BRAF (exon 15), CTNNB1 (exon 3), and PIK3CA (exons 10 and 21)." (PMID 20229506, 2010). "These tumours were MSI-H, and had no BRAF (V600E) mutations or methylation of MMR genes." (PMID 20051945, 2010). "Tumours in which the duplication occurs without this in-frame fusion or in patients with trisomy of the full chromosome 7 require other mechanisms to activate BRAF and induce oncogenesis." (PMID 19603027, 2009). "In three cases in which the tumour was negative, cfDNA was BRAF+." (PMID 19861964, 2009).
tumor (continued). "In fact, patients without K-Ras or BRAF gene mutation, or with normal PTEN protein expression at primary tumour level, may become resistant if their metastases show alterations of these gene or proteins." (PMID 19293803, 2009). "Notably, in ultraselect patients with right-sided tumors characterized by specific gene alterations (RAS/BRAF/EGFR ectodomain wild type), early tumor shrinkage and depth of response may serve as prognostic markers for chemotherapy plus anti-EGFR antibody treatment." (PMID 40280867, 2025). "The potential mechanism may involve BRAF pathway inhibitors downregulating MAPK signaling, thereby reversing the immunosuppressive properties of tumor cells (e.g., by increasing CD8+ T cell infiltration) and simultaneously enhancing tumor cell-intrinsic immune-related expression." (PMID 41225509, 2025). "Additionally, genetic status data (KRAS, BRAF, and microsatellite instability), which may play an important role in the prognosis of the neoplasm, were not analyzed." (PMID 40560518, 2025). "In addition, the deletion of MTAP and CDKN2A/B genes is more frequent in cell lines than in tumor samples and may represent a key driving event in the absence of KRAS/BRAF/NRAS mutations." (PMID 38669365, 2024). "Moreover, in contrast with tumour tissue biopsies and cfDNA, it is noteworthy that only one CTC harboured a BRAFV600E mutation, which suggests that resistance to BRAF inhibitors may not be driven by BRAFV600E-mutated CTCs." (PMID 38177660, 2024). "In this study, BRAF copy number gain and high-level amplification were associated with unfavorable clinicopathologic characteristics, including higher NPI scores, larger tumor size, high-grade tumors, hormone receptor–negative status, and non-luminal subtypes, compared to patients with no CNAs." (PMID 38919805, 2024). "Patients who carried driver gene mutations (EGFR or BRAF mutations or ALK/ROS1 rearrangements), who received ICIs as neoadjuvant treatment or less than two cycles of ICIs, who were lost to follow-up, and who did not complete the tumor response assessment were excluded from the study." (PMID 37359565, 2023). "Recent studies demonstrated that response to BRAF+MEKi in patients with germline CDKN2A PVs was not inferior to data from clinical trials and real-world studies, while the response rate to immunotherapy was superior in CDKN2A PVs carriers, likely due to an increased tumor mutational load." (PMID 36901733, 2023). "Regarding molecular biomarkers, while patients with primary tumours harbouring BRAF mutation should not be considered for LT, there is no specific contraindication for RAS mutations, although these mutations are associated with a slightly worse prognosis compared with wild-type tumours." (PMID 36879000, 2023). "Thus, it has been suggested that a preoperative “neoadjuvant” therapy with a BRAF-directed therapy or, in case of BRAF non-mutated tumors, a mKI/checkpoint inhibitor combination can lead to tumor resectability in locally advanced ATC and optimize local tumor control." (PMID 36637521, 2023). "Based on our findings and previous reports, we hypothesize cells expressing BRAF V600E have the potential to form TNT-like connections with surrounding cells to transfer communicating lipid droplets and pro-resolving fatty acids that may rewire the immune response for a tumor promoting response." (PMID 35565240, 2022). "Likewise, cells spared by BRAF, HER2 and PI3K inhibition maintained the capacity to generate secondary tumors and re-grow following conclusion of treatment, even though reductions of CD44v6 expression and sphere-forming ability were observed in primary tumor xenograft-derived cells." (PMID 35158939, 2022).
tumor (continued). "However, since conditional expression of oncogenes, such as mutant BRAF, encompasses the majority of cells, there are no current models that reliably replicate tumor initiation and early events of the carcinogenic process within a preserved thyroid tissue microenvironment." (PMID 34379110, 2022). "Tumor immune microenvironment (TIME) is an essential factor permitting the development and progression of malignancy, but whether TIME participates in the prognosis of BRAF-mutated PTC has not yet been reported." (PMID 35757399, 2022). "Also, BRAF V600E showed a negative relationship with age and tumor size." (PMID 35646190, 2022). "Intriguingly, inhibition of MAPK signaling in BRAF-mutant thyroid cells resulted in translocation of YAP to the nucleus and activation of its transcriptional output, suggesting that it may play a role in orchestrating adaptive responses to the inhibition of the tumor driver." (PMID 36476495, 2022). "Our results are contradicting with this latter study since we reported BRAF V600E to be associated with a worse OS but not with PFS, something that could be due to the differences in age, tumor location and extent of surgical resection between both series of patients." (PMID 35363819, 2022). "Although the presence of BRAF mutations does not contraindicate the use of anti-EGFR antibodies, patients with BRAF mutant cancer have a poor prognosis due to the relative resistance of this tumor type to chemotherapy and often receive more aggressive therapeutic regimens." (PMID 35205799, 2022). "Importantly, BRAF inhibitor-resistant tumours remain sensitive to palbociclib treatment, while palbociclib in combination with a BRAF inhibitor induces rapid and sustained tumour regression in vivo without acquired resistance." (PMID 33572972, 2021). "Interestingly, it has been reported that mCRC patients with right-sided lesions, who normally present with worse disease outcomes compared to those with left-sided tumours, have shown improved responses to combined FOLFOXIRI and bevacizumab treatment irrespective of BRAF and RAS mutational status." (PMID 33669775, 2021). "In recent years, advances in molecular tumor research identified abnormalities in the mitogen-activated protein kinase/extracellular-signal- regulated kinase (MAPK/ERK) activation pathway, due to a mutation or fusion of the BRAF gene, that were present in pLGG but not in aLGG." (PMID 34828788, 2021). "Notably, tumor sequencing could explain 49% of cases without causal germline variants, somatic MLH1 promoter hypermethylation, or somatic variants in BRAF." (PMID 34397043, 2021). "Patient triage could be performed by a quick assessment of tumor burden and testing of biomarkers with predictive and prognostic value (such as immunohistochemistry for mismatch repair proteins; sequence variation analysis for KRAS [GenBank 3845], NRAS [GenBank 4893], and BRAF)." (PMID 34495337, 2021). "Furthermore, some hotspot allele frequencies within these driver genes were relatively low, including BRAF-V600E (0.10–0.30%) and KRAS-G12V (0.11–1.26%), which could be explained by examining samples at different tumor stages and of different histological types collectively." (PMID 32180799, 2020). "The worse prognosis in subjects whose tumor was submitted for KRAS and BRAF mutation analysis compared with those not analyzed could be explained by a need for more antitumor treatment in addition to CRS and HIPEC, where patients with unfavorable prognostic signs are selected for mutation analysis." (PMID 31571052, 2020). "By studying primary tumor specimens and comparing organoid-forming and non-organoid-forming tumors, we found that organoid cultures were more difficult to establish from tumors characterized as MSI, BRAF-mutated, poorly differentiated, and/or of a mucinous type." (PMID 32290033, 2020).
tumor (continued). "Combination BRAF inhibitor plus MEK inhibitor treatment has also been shown to promote the cleavage of gasdermin E and release of HMGB1, suggesting that it may in part regulate the tumour immune microenvironment through pyroptosis (an inflammatory type of programmed cell death)." (PMID 32645969, 2020). "Furthermore, BRAF inhibition can paradoxically activate wild-type CRAF, and continued monotherapy with vemurafenib following the onset of resistance may further support tumor progression." (PMID 32517051, 2020). "Unfortunately, MAPK blockade (BRAF and MEK inhibitors) significantly increased the expression of TNF-α and the number of TAMs including M1/M2 macrophages in patients biopsies, which mainly played an inhibitory role even though M1 macrophage might inhibit tumor growth." (PMID 31134073, 2019). "Although anti-EGFR agents do not confer any benefit to pre-treated BRAF-mt mCRC patients, these results suggest that they might be of value in the first-line treatment of such patients, especially if the goal of the treatment is tumour shrinkage." (PMID 31353365, 2019). "Since in non-V600 BRAF mutant tumor cells the MAPK pathway could still play a dominant role via CRAF in proliferation, survival and migration, we hypothesized that vertical inhibition of RAF and MEK may lead to enhanced therapeutic effects as found previously in V600 BRAF mutant cells." (PMID 29739364, 2018). "Thus, during this multi-step model of BRAF/MEK inhibitor resistance the initial effectors of tumour cell survival may no longer be required after the evolution of durable drug resistance and this has important clinical implications." (PMID 30237495, 2018). "In line with our previous reports of this trial where patients were classified according to either KRAS exon 2–3/BRAF or extended RAS tissue mutational status, adding cetuximab to chemotherapy and chemoradiotherapy did not significantly improve the outcome of wild-type tumours." (PMID 29362371, 2018). "Therefore, Wnt inhibition may prevent tumours developing from more serrated routes, which are often associated with a lack of APC mutation and carry BRAF or KRAS mutations." (PMID 29556067, 2018). "Furthermore, it seems that the combination of MMP/TIMP at the leading margin of each tumor may be able to create a fine-tuned microenvironment, regardless of MMP expression or baseline oncogenic BRAF mutation." (PMID 30509240, 2018). "Although CCA is not usually a hypervascular tumor, regorafenib is still considered to be a potential therapeutic agent against this disease since several molecular alterations, including the disruption of the MAPK pathway and the activation of Ras and BRAF mutations, have been described in CCA." (PMID 29371921, 2017). "RsCC has a higher rate of BRAF mutations and high microsatellite instability (MSI-H), both which have established prognostic importance, with MSI-H tumours shown to have a favourable prognosis, and BRAF a strong poor prognostic marker in non-MSI-H but not in MSI-H tumours." (PMID 28390415, 2017). "CCA is not usually a hypervascular tumor, but regorafenib is still considered a potential therapeutic agent for this disease since several molecular alterations, including the disruption of the MAPK pathway and the activation of Ras and BRAF mutations, have been described in CCA." (PMID 29371921, 2017). "While these issues are being sorted out, it remains an attractive hypothesis that if BRAF mutation itself is associated with an enhanced radiosensitivity to SRS, then the use of a lower marginal dose may decrease the risk of tumor hemorrhage without compromising LC in this group of patients." (PMID 27200295, 2016). "Activation of c-Met signaling and/or HGF up-regulation in the tumor microenvironment may confer resistance to RTKs-targeting cancer therapies already in clinical use, including epidermal growth factor receptor (EGFR) and v-RAF murine sarcoma viral oncogene homolog B1 (BRAF) kinase inhibitors." (PMID 27086914, 2016).